BCL2 (BCL2 apoptosis regulator)
Diseases named in the same sentence as BCL2 in open-access papers (continued):
Sharing a sentence is not in itself a finding about the gene and the disease.
tumor (continued). "Immunohistochemical staining revealed that the tumor cells were positive for CD34, CD99, and BCL2." (PMID 32638177, 2020). "Our results showed that the surviving tumor cells exhibited mesenchymal phenotype via activated JNK signaling, upregulated Bcl-2, and downregulated PUMA, and survived much better than control cells in shear flow, suggesting JNK-mediated EMT is correlated with enhanced survival of suspended CTCs." (PMID 33143160, 2020). "Similarly, inhibition of Bcl-2 by its specific inhibitor, ABT-199, can also enhance the killing effect of SAHA in C666-1R xenografted tumors as indicated by tumor growth curve and TUNEL staining." (PMID 32692721, 2020). "In addition to their direct anti-tumor effect, new targeted drugs (i.e. BTK inhibitors, PI3K inhibitors, and the Bcl-2 inhibitor venetoclax) have demonstrated the ability to modulate non-neoplastic immune cell populations." (PMID 33312177, 2020). "Consistent with the in vitro results, MGE significantly reduced tumor weights compared with FGE in mice transplanted with MCF-7 cells, and it regulated the expression of apoptosis-related proteins, such as Bcl-2, Bax, cytochrome c, cleaved caspase-3, and cleaved PARP, in the tumor tissues." (PMID 32774407, 2020). "Synergistic effects could be achieved through the combination of AMG-176 with venetoclax in AML tumor models and in primary patient samples at a tolerated dose, highlighting the potential for dual MCL1 and BCL2 inhibition." (PMID 33198338, 2020). "Similarly, another study also found that NC reduced tumor volume and tumor weight in mice via suppression of ERK, STAT3, and SHH pathways, and regulation of Bcl-2, Bax, CyclinD1, VEGF pathway." (PMID 31956371, 2020). "Therapeutic failure of pan-BH3 mimetics can be traced back to their lack of tumor specificity and their low affinity to some of the anti-apoptotic Bcl-2 proteins." (PMID 32580291, 2020). "In addition, consistent with the cell-based results of A549 and NCI-H358 cells, TUNEL assays and Western blots of Bcl-2 and PARP studies revealed that KCP10043F enhanced the induction of apoptosis in the tumor tissues of the xenograft model." (PMID 32150979, 2020). "With the clinical development and success of the BCL-2 inhibitor venetoclax in mind, MCL-1 inhibitors may become the next novel class of anti-tumor agents with considerable potential across different malignancies." (PMID 33308268, 2020). "Indeed, some anti‐ or pro‐apoptotic genes, as some members of BCL family, as BCL2 and BCL7A, can indirectly be involved with neoplasias due to their capacity to activate caspases." (PMID 32073752, 2020). "The tumor metastasis and drug sensitivity of CRC could be diminished by hsa-miR-139-5p targeting the BCL2 pathway." (PMID 32377269, 2020). "Based on these results, we identified that the intensity of BCL2 expression by tumor cells in DLBCL varies widely regardless of its proportion." (PMID 32606309, 2020). "For example, the expression of tumour suppressor miRNA-34a is usually relatively low in various cancers, such as PC, NSCLC, and ALL, and it has been identified as a tumour suppressor with multiple targets, including CD44, PD-L1, ZEB1, and BCL-2." (PMID 32340605, 2020). "Afterwards, immunohistochemical study of the tumour specimen confirmed moderate positivity of dihydropyrimidine dehydrogenase and absence of Bcl-2 expression." (PMID 32582369, 2020). "In BCL2‐nonaddicted tumor cells, in contrast, blockade of BCL2 by venetoclax increases susceptibility to the antitumor effect of BI‐D1870." (PMID 32420699, 2020).
tumor (continued). "Clustering of tumour and healthy lung samples in a 2D map using t-SNE algorithm based on the normalized expression levels of XIST, TSIX, hnRNPu, Bcl-2, and BRCA1, revealed that collectively these five genes -when assessed together- can have a diagnostic potential in both LUAD and LUSC." (PMID 33255394, 2020). "In GC, paired analysis showed significantly upregulated Ki67 proliferation marker and tight junction protein CLDN2 and downregulated anti-apoptotic BCL2 in tumor as compared to non-cancerous tumor-adjacent tissue." (PMID 32630408, 2020). "Since SOX2 and BCL-2 could affect signaling pathways known to exert some sort of influence on OKC and AB, and since these two genes may interact with each other in other tumor models, the study of their expression in OKC and AB seems to be opportune." (PMID 31967981, 2020). "Similarly, in AML patients, etomoxir also reduced CSCs and, in combination with the BCL-2 inhibitor ABT-737, significantly reduced the tumor mass." (PMID 32679735, 2020). "Although the anti-tumor activity of venetoclax was demonstrated across a panel of B-NHL cell lines, cell lines with high BCL-2 protein expression were significantly more sensitive to venetoclax compared to those with low BCL-2 protein expression." (PMID 32290241, 2020). "Hypoxic stress of tumor microenvironment induces the expression of BH3 domains of B-cell lymphoma 2 (Bcl-2)/adenovirus E1B 19-kDa protein-interacting protein 3 (BNIP3), which is involved in dissociation of Bcl-2–Beclin1 complex." (PMID 32547395, 2020). "It efficiently antagonizes various prosurvival members of the BCL‐2 family (BCL‐2, BCL‐xL, BCL‐w, but not MCL‐1 or A1) and increases the susceptibility of various tumor cells to apoptosis (reviewed in Ref." (PMID 32623836, 2020). "The Bax/Bcl2 ratio was significantly changed in B16 tumor cells but not in non-malignant L929 cells following Ar-plasma exposure." (PMID 32650505, 2020). "Proteins from transplanted tumor tissues were extracted for Western blot analysis, and the results displayed that levels of FTO, MYC, CDK2, CDK4, Ki-67, PCNA and Bcl-2 proteins in miR-96 antagomir group were downregulated, while AMPKα2 and Bax proteins were raised." (PMID 33183350, 2020). "Additionally, numerous targets of expressions which were observed in carcinogenesis and tumor progression were reported to be regulated by miR-34a, such as CD44, BCL2, NOTCH1, CDK4/6, MET, MYC, and many other molecules." (PMID 32391256, 2020). "The expression of Bax and caspase 3 but not Bcl2 was significantly increased after CAP treatment in B16 tumor cells in comparison to untreated controls." (PMID 32650505, 2020). "CurDD could inhibit or delay the growth of tumor in the higher extent than curcumin as demonstrated from the western blot analyses for VEGF secretion, COX-2, Bax and Bcl-2 expression." (PMID 31374932, 2019). "However, the addition of a fourth oncogene (BCL6, BCL2, P53dd, and CCND3) led to tumor formation with a median of 112 days." (PMID 31586074, 2019). "In addition, the tumor marker ALDH1 and cell proliferation- and apoptosis-related factors, including Cyclin A, Cyclin D, Caspase-3 and Bcl-2, played an important role in HCC development and cell proliferation and apoptosis processes." (PMID 30765768, 2019).
tumor (continued). "Furthermore, the expression levels of downstream genes regulated by NF-κB such as Survivin, Bcl-2, VEGF, and cyclin D1, were also determined, which were found to be involved in tumor survival and chemoresistance, angiogenesis, and proliferation, respectively." (PMID 31729451, 2019). "In addition, we detected proliferation-related proteins (Ki67, Bcl-2 and cyclin D1), CSCs core genes and DNMT3B levels in tumor grafts to investigate the mechanism by which antisense inhibition of piRNA-823 reduced the tumor volume in vivo." (PMID 30979371, 2019). "The results indicated that TMEA could significantly downregulate the expression of the antiapoptotic factors CD31 and Bcl-2 and upregulate the expression of proapoptotic factors Bax and caspase-3 in a dose-dependent manner in SW620 tumor tissues." (PMID 32047442, 2019). "In addition, HIF1A promotes autophagy by altering the expression of BCL2/adenovirus E1B 19 kDa protein-interacting protein 3 (BNIP3), which is part of a stress adaptation mechanism that promotes tumor cell survival and avoids cell death." (PMID 31744467, 2019). "Additionally, targeting antiapoptotic BCL2 signaling further sensitizes LNCaP cells to ENZ, demonstrating a potential strategy to prevent acquired drug resistance in initially sensitive tumor cell populations." (PMID 31228231, 2019). "Thus, immunohistochemistry (IHC) investigation demonstrated that ECPU-0001 treatment clearly reduced expression of BCL-2 and BCL-2-xL, while enhanced expression of BAX in tumor." (PMID 31450709, 2019). "Moreover, IHC assay exposed that the Luc-YAP-shRNA group exhibited less YAP, Bcl-2 and KI-67 staining, indicating that YAP-downregulated suppressed tumor growth of Hep-2 in vivo." (PMID 31269911, 2019). "This network demonstrates that 61 exosomal molecules may affect tumor progression through pathways controlled by key components including MET, Ras, RAF1, Mek, ERK1/2, MITF, BCL2, PI3K, Akt, mTOR, PD-1, KIT, JAK STAT3, or ETS1." (PMID 31681332, 2019). "FLs were divided according to BCL2-break (positive, negative and NA) and according to tumor grading (1, 2 and 3a)." (PMID 31039827, 2019). "Its tumor suppressor role was demonstrated by targeting MAP2K4 and BCL2." (PMID 30945144, 2019). "In conclusion, we convincingly demonstrate that BCL-XL and MCL-1 but not BCL-2 are highly expressed in tumor tissues of SCCHN patients." (PMID 31801952, 2019). "Furthermore, the antitumor activity of TMEA was evaluated in SW620 tumor xenograft bearing in nude mice in vivo and the expressions of CD31, Bcl-2, Bax, and caspase-3 were investigated in SW620 tumor tissues by immunohistochemical analysis." (PMID 32047442, 2019). "Pro-apoptotic factors such as BAX, BAK, and Bad and the anti-apoptotic factors Bcl2 and Bcl-xl are delicately balanced, and this balance is often lacking in tumor cells." (PMID 30686270, 2019). "Compared to Glycyrrhetinic acid-free co-delivery system (siRNA/DOX/DPP) and GH-DPP nanoparticles for delivery of DOX or Bcl-2 siRNA alone, siRNA/DOX/GH-DPP nanoparticles could induce more cellular apoptosis, and showed higher anti-tumor effect." (PMID 30723405, 2019). "We therefore hypothesize that tumor cells with concurrent MYC and BCL2 overexpression, such as DHL, may be effectively targeted through the combined treatment with XPO1 and BCL2 inhibitors." (PMID 31752970, 2019). "This is also true in other tumour lineages, such as CRC; however, whereas increased BIM and BMF primed CRC cells to undergo substantial apoptosis following treatment with the BCL2/BCL-w/BCL-XL inhibitor navitoclax/ABT-26311,25,26, this combination was notably less effective in melanoma." (PMID 31727888, 2019).
tumor (continued). "Moreover, we observed significantly increased apoptotic cells in zoledronic acid-treated tumor tissues using the TUNEL assay, and the expression of Bcl-2 was up-regulated and Bax was down-regulated." (PMID 30791957, 2019). "TTP has been shown to downregulate several well-established markers for tumor progression like BCL2, VEGFA, and MYC in non-liver tissue." (PMID 31717307, 2019). "BCL-2 synergizes with MYC in tumor progression, as observed in transgenic mice, and this cooperation seems to involve the capacity of BCL-2 to block MYC-induced apoptosis in lymphoid cells, without affecting the mitogenic function of MYC." (PMID 29747654, 2018). "In addition, the stemness marker proteins CD44, Oct-4, Nanog, as well as Bcl-2 and MMP-9 expression levels of ALDH+ cells were upregulated compared with the original tumor cells, indicating that they have certain stem cell characteristics." (PMID 29914196, 2018). "Having demonstrated that Bcl-2-expressing CD-NSCs show prolonged viability, it was important to confirm that the Bcl-2 modification did not transform CD-NSCs into tumor-initiating cells." (PMID 30026762, 2018). "The lowest Bcl-2/BAX ratio was detected for control samples and the highest for tumour samples." (PMID 29515335, 2018). "The Δ% of K showed a highly positive correlation with the Δ% of Ki-67 and CA125, moderately positive correlation with the Δ% of tumor size and Bcl-2, and moderately negative correlation with the Δ% of apoptosis and tumor necrosis." (PMID 30518386, 2018). "Moreover, we observed a statistically significant correlation when comparing the tumor mass from animals with FAM3B gene expression (r = 0.8932; p = 0.0062) and Bcl-2 gene expression (r = 0.9274; p = 0.0026) in all animals." (PMID 29357840, 2018). "According to previous reports, the staining could be judged as positive if the number of tumor cells positive for C-MYC ≥ 40%, BCL-2 ≥ 50%, or BCL-6 ≥ 30% of tumor tissues." (PMID 30666200, 2018). "Consistent with this diagnosis, some neoplasms of this group also express cytosolic IgG as demonstrated by FACS and immunoblotting of protein extracts of lymphoid tissues from representative TRAF3/BCL2 double-tg mice with this type of lymphoid expansions." (PMID 30687320, 2018). "Furthermore, we demonstrated for the first time that Bcl‐2 mRNA destabilization by TTP and AUF1 plays a functional role in the suppression of tumor growth by adiponectin." (PMID 30524947, 2018). "Furthermore, intravenous delivery of the selected siRNAs aiming to suppress the expression of ER/BCL2 and ER/ERBB2/EGFR groups of proteins led to a significant retardation in tumor growth in a 4T1-induced syngeneic mouse model." (PMID 29932151, 2018). "Moreover, SPS significantly inhibited the growth of the tumor xenograft, with similar changes in the expression of Bcl-2, COX-2, Bax, and cleaved caspase-3 in the tumor xenograft to the in vitro analysis." (PMID 30103745, 2018). "Furthermore, systemic delivery of the nanoparticles carrying the siRNAs to suppress the expression of ER/BCL-2 and ER/ERBB2/EGFR groups of proteins resulted in a notable and sustainable decrease in tumor growth in a 4T1-induced syngeneic mouse model." (PMID 29932151, 2018). "Inhibition of Bcl-2 did not lead to a significant reduction in tumor growth as a single agent nor in combination with doxorubicin." (PMID 30242253, 2018). "Moreover, in our study Bax was upregulated after knockdown of HOTAIR, on the other hand, Bcl-2 with low expression levels, this is probably an indirect argument that HOTAIR promotes tumor development and progression in CCA36–40." (PMID 30111807, 2018).
tumor (continued). "Moreover, antiapoptotic factor Bcl-2 and the migration related protein MMP-9 were significantly increased in ALDH+ cells compared with ALDH− tumor cells." (PMID 29914196, 2018). "Tumour grade along with immunohistochemistry for Ki67, STAT6, PHH3, CD34 and Bcl-2 were assessed." (PMID 30183767, 2018). "In vivo, selective inhibition of Bcl-xl, but not Bcl-2 resulted in a decrease in tumor growth rate, even though no sensitization to doxorubicin was observed." (PMID 30242253, 2018). "Consistent with the expression changes in HN-6 cells after different treatment, Bcl-2 and COX-2 expression in the tumor xenografts from the SPS or cisplatin groups was significantly lower than those from the model group, and the expression of Bax and cleaved caspase-3 was increased." (PMID 30103745, 2018). "BCL-2 was reported to have a role in tumor onset, spread and therapy resistance that does not rely uniquely on the apoptotic pathway." (PMID 29570632, 2018). "We evaluated the expression levels of the following five genes associated with DNA damage, carcinogenesis, and/or chemoprevention mechanisms: the tumor suppressors ETV6 and PTEN, the cell death regulators BCL2 and BAX (anti- and proapoptotic, respectively), and the protooncogene ABL1." (PMID 30370304, 2018). "We also compared the levels of the anti-apoptotic proteins, BCL2 and IRF4, in the two tumor types." (PMID 30125329, 2018). "Accumulating evidence has been proven that PP2A as a tumor suppressor could reverse the actions of protein kinases by dephosphorylating PP2A substrates β-catenin, c-Myc, and Bcl-2 from threonine and serine residues of proteins." (PMID 29986744, 2018). "Furthermore, it has been reported that the presence of increased METTL3 levels in AML leads to higher m6A methylation levels of BCL2 and PTEN and promotes the translation of BCL2 and PTEN mRNA, which ultimately leads to tumour formation." (PMID 30031372, 2018). "Interestingly, when we analyzed the BCL-2/MCL-1 ratio, predictive value of the observed ABT-263 efficacy, we distinguished a parallelism between tumor growth and BCL-2/MCL-1 levels among sorafenib-only treated tumors (n=11)." (PMID 29682179, 2018). "In other words, the bacterial prodigiosin may increase the ratio of Bax to Bcl-2 in JEG3 cells, PC3 cells, JEG3 tumor and PC3 tumor." (PMID 30400387, 2018). "In vivo, AP/PTX-SLNs were revealed to be much more effective in suppressing tumor growth in B16F10-bearing mice and in eliminating cancer cells in the lungs than single drug (AP or PTX)-loaded SLNs via a synergistic effect through reducing the Bcl-2/Bax ratio." (PMID 28856937, 2017). "We also explore the effects of this inhibitor in combination with novel agents, including the BCL-2 inhibitor (Venetoclax), CDK-9 inhibitor (BAY-1143572), and p110δ-PI3K inhibitor (Idelalisib), as a means of uncovering complimentary anti-tumor pathways that can be targeted." (PMID 29383130, 2017). "Our results support that the Bcl-2/Twist1 complex induces EMT and facilitates tumor metastasis in OSCC, which might represent a powerful strategy for developing of novel OSCC therapies." (PMID 28032603, 2017). "Interrogating apoptotic molecules upstream of caspase 3 revealed a dramatic decrease in BCL2 expression following overexpression of the IFIT genes, suggesting that the IFIT genes promote sensitivity to apoptosis of the tumor cells." (PMID 28878208, 2017).